CRP (C-reactive protein)
Diseases named in the same sentence as CRP in open-access papers (continued):
Sharing a sentence is not in itself a finding about the gene and the disease.
Obesity (continued). "A low grade of obesity assessed by BMI was present in the T2DM group, diminishing the effects of obesity in serum hs-CRP levels." (PMID 24772446, 2014). "For CRP we could not find any significant interaction between glucose tolerance group and waist circumference, thus our results did not indicate that the association between obesity and the inflammation marker depends on the degree of glucose tolerance." (PMID 24681553, 2014). "However, the association between obesity measurements and CRP-mf-4 was not continuous." (PMID 25299074, 2014). "Reports show that women with PCOS, both with obesity and normal weight, exhibit elevated serum TNF, C-reactive protein (CRP), monocyte and lymphocyte circulating levels, and inflammatory infiltration in ovarian tissue." (PMID 25763405, 2014). "Inflammatory mediators, including C-reactive protein (CRP), interleukin-6 (IL-6), IL-1β, and tumour necrosis factor α (TNFα), are systemically elevated in obesity in animal and human models." (PMID 24967364, 2014). "Fourth, obesity induces chronic low-grade inflammation resulting in an increase of local and systemic levels of cytokines (such as TNF-α, interleukin-6 (IL-6), C-reactive protein (CRP), and monocyte chemoattractant protein-1 (MCP-1))." (PMID 23431300, 2013). "There is evidence of increased circulating CRP and IL-6 levels in COPD whereas in OSA obesity is a major confounding variable and the evidence of an independent relationship between OSA and CRP/IL-6 levels is less clear." (PMID 24256627, 2013). "Higher levels of C-reactive protein (CRP) and lower levels of high-molecular-weight (HMW) adiponectin have been both reported to correlate with obesity and metabolic syndrome." (PMID 24069195, 2013). "As obesity per se is considered a subclinical inflammation, the increased levels of TNF-α and CRP in breast cancer cases in the present study are consistent with stress-induced inflammation among newly diagnosed breast cancer patients." (PMID 23374911, 2013). "The main factors associated with UA increase were altered BMI (overweight and obesity), muscle hypotrophy (MMI), higher levels of urea, triglycerides, and CRP." (PMID 23311699, 2013). "We have previously demonstrated that oxidative stress in the Inuit is related to obesity-induced inflammation and F2-IsoPs and IsoFs were both related significantly to SBP and CRP." (PMID 23670530, 2013). "Previous studies evaluating the relationship between adiposity and concentrations of CRP and SAA have used anthropometric measures of obesity including body mass index (BMI, kg/m2), waist circumference, and bioelectrical impedance." (PMID 22873489, 2012). "In particular, while among current smokers high WC, above normal BMI (overweight/obesity), and elevated BP were less frequent, current smokers had higher prevalence of low HDL-C, high plasma TG and elevated CRP." (PMID 22716943, 2012). "As with the short pentraxin CRP, PTX3, a member of the long pentraxin family, has been suggested to comprise a mechanistic link between chronic low-level inflammation and obesity." (PMID 22509348, 2012). "Importantly, obesity is associated with chronic low-grade inflammation, and a high-fat diet increases the proinflammatory cytokines IL1-β, tumor necrosis factor alpha (TNF-α), C-reactive protein (CRP), and IL1-6 and stimulates inflammatory signaling in adipose, serum, liver, and brain." (PMID 22144990, 2011). "Thereafter, the concept was enforced by abundant literatureidentifying increases in many other inflammatory cytokines, such as plasmaC-reactive protein (CRP), interleukin 6 (IL-6), plasminogen activatorinhibitor-1 (PAI-1), in models of obesity." (PMID 20606248, 2010). "Obesity itself is regarded as a proinflammatory state with oxidative stress showing increased levels of TNF-α, IL-6, and C-reactive protein (CRP)." (PMID 19545363, 2009).
Obesity (continued). "Plasma levels of CRP, TNF-α, and IL-6, which are markers of inflammation, are elevated in obesity, insulin resistance, essential hypertension, type 2 diabetes, and CHD both before and after the onset of these diseases." (PMID 18078524, 2007). "Nowadays, CRP is considered as an independentbiomarker for the development of CVD which emphasizes the connection between inflammation, obesity, and CVD." (PMID 17389767, 2007). "Obesity can induce a state of leptin and insulin resistance, chronic low-grade inflammation, and increased leptin, tumour necrosis factor (TNF)-α, IL-6 and C reactive protein serum levels." (PMID 16160698, 2005). "Adiponectin was inversely associated with obesity, abdominal obesity and sarcopenic obesity, but these associations were no longer significant after further adjustment for HOMA‐IR, CRP and irisin." (PMID 41457869, 2026). "Unlike the present study, which showed null findings, the only other study that used a similar sample of exclusively postmenopausal women with obesity (BMI 30–35 kg/m2) enrolled 28 participants, tested a lower dose of 449 mg EGCG/day for 60 days, and found a significant reduction in serum CRP." (PMID 41515260, 2026). "Therefore, we conducted a meta-analysis to examine the role of HIT on pro-inflammatory cytokines including C-reactive protein (CRP), interleukin 6 (IL-6), and tumor necrosis factor-alpha (TNF-α) in children with overweight/obesity." (PMID 41590696, 2026). "If ESR, unlike CRP, won't be affected by obesity or metabolic syndrome, then it can be a better alternative to our problem." (PMID 41458786, 2025). "Obesity is commonly considered a condition characterized bylow-grade chronic inflammation, in which macrophages in adipose tissue,especially in abdominal fat, are activated and release pro-inflammatory markerssuch as TNF-α, interleukin-6 (IL-6), and CRP." (PMID 40926826, 2025). "The induction of obesity (group 2) led to a significant increase in all monitored inflammatory interleukins compared to the control group (group 1), as observed for IL-1β, IL-6, IL-8, TNF-α, and C-reactive protein, with p < 0.0001 in all cases." (PMID 40565191, 2025). "Several reviews have put forward CRP as a predictor of metabolic syndromes, non-alcoholic fatty liver disease and obesity, independent of inflammatory disease." (PMID 40552303, 2025). "Obesity activates various proinflammatory pathways, which includes elevated level of cytokines such as tumor necrosis factor-α (TNF-α), interleukin-6 (IL-6), C-reactive protein (CRP), plasminogen activator inhibitor-1 (PAI-1), and leptin." (PMID 40893881, 2025). "Sixth, This study only examined the relationship between IL-6, TNF-α, and IL-2 levels and psychiatric symptoms and obesity, without testing other factors, particularly C-reactive protein (CRP) and interleukin-10 (IL-10)." (PMID 40791199, 2025). "Obesity drives chronic low-grade systemic inflammation, characterized by elevated levels of pro-inflammatory cytokines, including tumor necrosis factor alpha (TNF-α), interleukin (IL)-6, and C-reactive protein (CRP)." (PMID 40703374, 2025). "Our mediation analyses revealed that CRP partially mediates the relationship between the METS-VF and chronic pain, supporting the “obesity-inflammation-pain” axis hypothesis." (PMID 40444245, 2025). "Alongside these, inflammatory cytokines such as tumor necrosis factor-alpha (TNF-α), interleukin-6 (IL-6), and C-reactive protein (CRP) are significantly influenced by changes in adipose tissue dynamics and play a central role in the development of obesity-related complications." (PMID 40710568, 2025). "Similarly, omentin—secreted by visceral fat stromal cells—demonstrates anti-inflammatory properties, with inverse correlations reported between its circulating levels and markers such as CRP, IL-6, and TNF-α in individuals with obesity." (PMID 40868054, 2025).
Obesity (continued). "Importantly, research has identified IR and systemic inflammation as central mediators in the obesity-NAFLD link, with both HOMA-IR and CRP demonstrating strong and consistent mediation effects." (PMID 40855535, 2025). "Overweight/obesity, SII, and CRP are associated with the therapeutic efficacy of non-lactational mastitis." (PMID 41551509, 2025). "Fifth, additional factors such as comorbidities, including obesity or other inflammatory conditions, may contribute to higher DAS-28 scores, CRP, and ESR values in poor responders." (PMID 40732356, 2025). "Probasco and his colleagues found that elevated CRP and ESR levels in preoperative inflammation are positively correlated with BMI, and they believed that traditional biomarkers should be used with caution in the diagnosis of obesity PJI." (PMID 40041151, 2025). "Similarly, the Complement Activation Network, characterized by increased C9 and CRP and decreased C1QB, aligned with the chronic low-grade inflammation observed in obesity." (PMID 40981199, 2025). "Nevertheless, they retain their diagnostic utility, especially when combined with other markers such as Gal-3 or high-sensitivity C-reactive protein (hs-CRP) to rule out confounding factors such as obesity or renal dysfunction." (PMID 40129519, 2025). "Patients with obesity at baseline had higher CRP at follow-up compared to patients that were non-obese." (PMID 41141372, 2025). "Likewise, C-reactive protein (CRP) levels, a clinical marker of inflammation and commonly elevated in obesity, appear normal." (PMID 40149538, 2025). "In addition to the significant reductions in C-reactive protein and NT-proBNP reported in the STEP-HFpEF trial with semaglutide use in patients with obesity and HFpEF, a subsequent substudy demonstrated further favorable effects." (PMID 40703631, 2025). "Studies have demonstrated that individuals with obesity exhibit significantly higher plasma concentrations of CRP and IL-6 compared to those with overweight, independent of age, sex, and metabolic comorbidities." (PMID 40868054, 2025). "Given this, we hypothesized that inflammatorymarkers such as CRP and NLR play a different mediating role in the relationshipbetween obesity and depression in women compared with men." (PMID 40926826, 2025). "Although CRP displayed a high AUC in this cohort, it is a non-specific acute-phase reactant that can be influenced by infection, obesity, and age-related inflammation." (PMID 41375740, 2025). "Moreover, chemerin levels in newly diagnosed hypertensive patients were significantly higher than in normotensive controls and positively correlated with inflammatory markers (hs-CRP, TNF-α, and IL-6), obesity parameters, plasma TGs, and HOMA-IR index." (PMID 40564199, 2025). "C-reactive protein (CRP), an important inflammatory marker shown to be positively correlated with obesity, may also impact male fertility, especially in obese individuals." (PMID 39941454, 2025). "Although high-sensitivity C-reactive protein (hs-CRP) is widely used, its non-specificity is high, and no consensus exists on a specific cut-off value that defines chronic, obesity-related inflammation in a child." (PMID 41561055, 2025). "Obesity is characterized by chronic low-grade inflammation driven by adipose-derived cytokines/adipokines (e.g., interleukin-6 (IL-6), plasminogen activator inhibitor-1 (PAI-1), and C-reactive protein (CRP)) and immune remodeling in adipose tissue." (PMID 41373857, 2025). "The data from participants with NAFLD and obesity showed a negative correlation of eGDR with liver fibrosis, and a positive correlation of CRP and WBC with liver fibrosis." (PMID 40158190, 2025). "Subgroup analysis revealed that consumption of propolis in individuals with metabolic syndrome or obesity did not have a significant impact on the serum CRP levels." (PMID 40421039, 2025).
Obesity (continued). "Overall, our systematic review showed that CRP is not a perfect biomarker for monitoring individual treatment response, which is in part due to various confounding factors, such as obesity affecting its level." (PMID 41458786, 2025). "In multivariable linear regression analyses, use of bDMARDs (β −0.22, p = 0.03) at follow-up were associated with lower LV mass index at follow-up, independent of C-reactive protein (CRP), age, sex, and obesity at baseline." (PMID 41141372, 2025). "Additionally, the consistency of the G/L ratio, CRP, procalcitonin (PCT), ferritin, age, and obesity as biomarkers for predicting both disease severity and mortality reinforces their importance in clinical practice." (PMID 38793085, 2024). "Our hypotheses were as follows: (i) hs-CRP levels are higher in individuals with MHO and MUO compared to those with metabolically healthy non-obesity (MHNO)." (PMID 39519093, 2024). "Interestingly, high levels of CRP are positively correlated with an increase in LRG1 and HPX, suggesting the potential interplay between these proteins in the context of obesity." (PMID 39339686, 2024). "Abdominal obesity is considered to be an inflammatory state, and many inflammatory factors come from visceral adipose tissue, such as IL-6, TNF-α, C-reactive protein (CRP), leptin, etc., which may lead to obesity-related airway inflammation." (PMID 38926790, 2024). "Obesity has a significant inflammatory component and overweight individuals have increased serum levels of inflammatory cytokines such as tumor necrosis factor alpha (TNF-α), CRP and interleukins (IL-6, IL-18)." (PMID 38330593, 2024). "A meta-analysis revealed that women with PCOS exhibit an increase in circulating CRP that is independent of obesity." (PMID 39063189, 2024). "The significant reduction in CRP during the CMD phase compared to placebo underscores CMD’s role in alleviating inflammation, making it a promising intervention for managing chronic inflammation in obesity." (PMID 39770957, 2024). "Aside from the higher CRP levels observed at T2 of AP patients with obesity (compared to overweight patients), no other significant differences were observed considering subgroups according to BMI." (PMID 38673560, 2024). "In a randomized control trial, women suffering from obesity were treated with 3 g/day of N. sativa oil with calorie-restricted diet and displayed lower inflammatory biomarkers levels (TNF-α and C-reactive protein (CRP)) compared to control." (PMID 38543686, 2024). "Moreover, obesity changes the baseline levels of serum cytokines/adipocytokines IL-6, TNF-α, and CRP/hs-CRP." (PMID 39564133, 2024). "Women with PCOS exhibit elevated serum concentrations of TNF and C-reactive protein (CRP), along with increased levels of monocytes and lymphocytes, and obesity and hyperinsulinemia could further exacerbate the chronic inflammatory condition." (PMID 38978626, 2024). "Adjustment of model 3 by CRP instead of suPAR revealed a similar dampening of the association between categorized obesity and the composite outcome (class III obesity vs nonobese reference, adjusted OR [aOR] 1.18 [95% CI, 0.88-1.59])." (PMID 38635301, 2024). "Cr supplementation decreased the expression of liver nuclear factor kappa-B (NF-κB) p65, and lowered plasma levels of C-reactive protein (CRP), monocyte chemoattractant protein-1 (MCP-1), and intercellular cell adhesion molecule-1 (ICAM-1) in animal models of obesity, metabolic syndrome and T2DM." (PMID 38721033, 2024). "In obesity, various cellular and molecular processes induce inflammation, especially in adipose tissues, which leads to the release of inflammatory mediators like tumor necrosis factor α (TNF-α), C-reactive protein (CRP), and interleukin 6 (IL-6)." (PMID 38725575, 2024). "In addition to CRP, increased nitric oxide, tumor necrosis factor alpha (TNF-α), and IL-6 have been reported in women with overweight/obesity." (PMID 39236809, 2024).
Obesity (continued). "On the other hand, the relation between CRP concentrations and insulin resistance or reactive hyperinsulinemia is independent of obesity." (PMID 38255379, 2024). "In AT of people with obesity, the secretion of cytokines such as TNF-α and IL-6 is upregulated, which stimulates the hepatic release of acute-phase proteins such as C-reactive protein (CRP)." (PMID 38474344, 2024). "Negative correlations of serum adiponectin with CRP were observed in healthy controls, in obesity patients, in patients with metabolic diseases, and in acute dengue patients." (PMID 38791005, 2024). "Integration of obesity markers into our regression model revealed CRP was a covariate of BMI, independent of age, sex, and ethnicity." (PMID 38172612, 2024). "In ACPA-negative RA patients, CRP levels did not significantly differ for patients with overweight or obesity compared with normal weight patients (β0.17, 95% CI − 1.82, 2.15 and β1.02, 95% CI − 1.29, 3.33, respectively)." (PMID 38321544, 2024). "The study found higher median CRP concentrations in women with obesity than in those with normal weight." (PMID 39769504, 2024). "Moreover, adipose tissue in older adults with obesity functions as a dynamic endocrine organ, secreting an array of hormones and pro-inflammatory cytokines, like TNF-a, IL-1a, IL-6, and CRP." (PMID 38668557, 2024). "On the other hand, elevated levels of CRP are found in obesity, for example, regardless of the presence of IRD." (PMID 39124816, 2024). "Additionally, the presence of Th1 cells in visceral adipose tissue has been found to be significantly correlated with plasma C-reactive protein (CRP) levels, suggesting their involvement in obesity-driven inflammatory processes." (PMID 39148730, 2024). "It was found that overall cancer risk was positively associated with many inflammation biomarkers (like CRP, GLO, CAR, AISI, etc.), regardless of obesity status." (PMID 39314636, 2024). "Laboratory tests were requested (blood count, ESR, C-reactive protein, rheumatoid factor, antinuclear factor, thyroid-stimulating hormone [TSH], and free T4), and psychological, psychiatric and endocrinological follow-up was advised, the latter due to obesity." (PMID 39247631, 2024). "Inflammatory markers measured in obesity-related studies often include IL-6, TNF-α, and CRP." (PMID 38792936, 2024). "As adipose tissue is assumed to have immunomodulating and proinflammatory properties, obesity could potentially increase local and systemic inflammation as measured by SJC and CRP." (PMID 38321544, 2024). "A possible hypothesis is the elevated serum levels of IL-6, C-Reactive Protein (CRP), TNF-α, and leptin in obesity may induce inflammatory response in the IVD." (PMID 37959372, 2023). "At 1 year after anti-obesity treatments, there was a significant reduction in BW (average PWL = 5%), BMI and WC, and a significant improvement in glycemia, insulin sensitivity indices, and CRP levels." (PMID 37436597, 2023). "Semaglutide also improved 6MWD, resulted in a greater number of wins versus placebo for the composite hierarchical endpoint and reduced systemic inflammation assessed by CRP in each obesity class, with no heterogeneity of treatment benefits." (PMID 37635157, 2023). "Therefore, the aim of our study was to assess the relationship between selected measures of obesity (BMI, WC, RFM, VAI, WHtR) and parameters of chronic inflammation (CRP, TNF-α, IL-6) in perimenopausal women." (PMID 37375693, 2023). "Patients with obesity treated with rituximab had a greater decrease in delta CRP levels between baseline and 6 months than patients without obesity (p = 0.031)." (PMID 38813042, 2023). "On day 7, the patients without obesity had significantly higher levels of CRP than patients with obesity (61.1 and 51.7 mg/L, respectively)." (PMID 37240496, 2023).